ANTXRL (ANTXR like)
Tractability: Antibody: UniProt predicts a signal peptide or a membrane-spanning region; its Gene Ontology location is reachable by antibodies, with medium confidence.
Gene: Protein-coding gene on chromosome 10 (46,286,345 to 46,330,727, forward strand). Ensembl gene ENSG00000274209.
Subcellular location: Membrane
Gene Ontology:
Molecular function: transmembrane signaling receptor activity; signaling receptor activity
Cellular component: cell surface; plasma membrane; membrane
Genetic constraint (gnomAD): Loss-of-function variants: 58 observed, 71.91 expected, observed/expected ratio (o/e) 0.81, 90% interval 0.65 to 1. The upper end of that interval is the gene's LOEUF score, 1, which puts it in group 4 of 6, group 1 being the genes least tolerant of losing a copy. Missense variants: 734 observed, 737.28 expected, observed/expected ratio (o/e) 1, 90% interval 0.94 to 1.06. Synonymous variants: 321 observed, 273.64 expected, observed/expected ratio (o/e) 1.17, 90% interval 1.07 to 1.29.
Homologues: Orthologues: chimpanzee ANTXRL (94% identical), mouse Antxrl (42% identical), rat Antxrl1 (40% identical), dog ANTXRL (39% identical), tropical clawed frog antxrl (31% identical), zebrafish antxr1c (30% identical), mouse Gm30083 (28% identical), rat AABR07024652.1 (28% identical), zebrafish antxr1d (26% identical). Paralogues in human: ANTXR1 (29% identical), ANTXR2 (26% identical).
Diseases named in the same sentence as ANTXRL in open-access papers:
ANTXRL is named in the same sentence as 10 diseases in open-access papers, as found by Europe PMC text mining. Sharing a sentence is not in itself a finding about the gene and the disease. The quoted sentences say what the papers report.
bipolar disorder (2 papers, 2015 to 2021). A disorder of the brain that causes unusual shifts in mood, energy, activity levels and the ability to carry out day-to-day tasks. "ANTXRL and CHST9 are located in the CNV regions associated with bipolar disorder and autism." (PMID 26136833, 2015).
schizophrenia (2 papers, 2015 to 2021). A major psychotic disorder characterized by abnormalities in the perception or expression of reality. "In the candidate CNV regions, 26 regions had no overlaps with the common CNVs found in Asian populations and included the genes (i.e., ANTXRL, CHST9, DNM3, NDST3, SDK1, STRC, SKY) that are associated with schizophrenia and/or other psychiatric diseases." (PMID 26136833, 2015).
endometrial cancer (1 paper, 2024). Primary or metastatic malignant neoplasm involving the endometrium (mucous membrane that lines the endometrial cavity).
infection (1 paper, 2015). The state of being infected such as from the introduction of a foreign agent such as serum, vaccine, antigenic substance or organism. "ANTXRL did not have detectable gene expression in any of the nine observations at 12 h post-infection." (PMID 26426037, 2015).
ANTXRL also shares sentences with these, for which no sentence is quoted: Alzheimer disease (1 paper); autism (1); Esotropia (1); HIV-1 infection (1); Parkinson disease (1); psychiatric diseases (1).